RAB39A (RAB39A, member RAS oncogene family)
Description:
The small GTPases Rab are key regulators of intracellular membrane trafficking, from the formation of transport vesicles to their fusion with membranes. Rabs cycle between an inactive GDP-bound form and an active GTP-bound form that is able to recruit to membranes different sets of downstream effectors directly responsible for vesicle formation, movement, tethering and fusion. RAB39A regulates autophagosome-lysosome fusion via recruitment of the HOPS endosomal tethering complex onto lysosomes; this process involves lysosomal RAB39A and autophagosomal RAB2A recruitment of HOPS subcomplexes VPS41-VPS16-VPS18-VPS33A and VPS39-VPS11, respectively, which assemble into a functional complex to mediate membrane tethering and SNAREs-driven membrane fusion. Also negatively regulates lipopolysaccharide (LPS)- induced autophagosome formation in macrophages, possibly by implicating PI3K. Promotes the delivery of MHC-I molecules from the ER to phagosomes and the generation of peptide-loaded MHC-I complexes in phagosomes, thus enhancing antigen cross-presentation by dendritic cells (By similarity). Plays a role in the maturation and acidification of phagosomes that engulf pathogens, such as S.aureus and M.tuberculosis. Plays a role in the fusion of phagosomes with lysosomes. May be involved in multiple neurite formation (By similarity).
Synonyms: RAB39; K28
Tractability: Antibody: UniProt places it where antibodies can reach, with high confidence; its Gene Ontology location is reachable by antibodies, with medium confidence. PROTAC: ubiquitination databases record sites on it.
Target class: Enzyme; Hydrolase
Gene: Protein-coding gene on chromosome 11 (107,928,448 to 107,963,482, forward strand). Ensembl gene ENSG00000179331.
Subcellular location: Cell membrane; Cytoplasmic vesicle, phagosome membrane; Lysosome membrane; Autolysosome membrane
Pathways (Reactome):
Vesicle-mediated transport: Intra-Golgi traffic; RAB GEFs exchange GTP for GDP on RABs
Metabolism of proteins: RAB geranylgeranylation
Gene Ontology:
Molecular function: G protein activity; protein binding; GTP binding; GTPase activity
Biological process: autophagosome-lysosome fusion; phagosome acidification; phagosome-lysosome fusion; vesicle-mediated transport; Rab protein signal transduction
Cellular component: autolysosome membrane; lysosomal membrane; phagocytic vesicle; cytosol; Golgi membrane; late endosome membrane; phagocytic vesicle membrane; plasma membrane
Genetic constraint (gnomAD): Loss-of-function variants: 17 observed, 21.41 expected, observed/expected ratio (o/e) 0.79, 90% interval 0.54 to 1.19. The upper end of that interval is the gene's LOEUF score, 1.19, which puts it in group 5 of 6, group 1 being the genes least tolerant of losing a copy. Missense variants: 234 observed, 269.9 expected, observed/expected ratio (o/e) 0.87, 90% interval 0.78 to 0.97. Synonymous variants: 99 observed, 104.14 expected, observed/expected ratio (o/e) 0.95, 90% interval 0.81 to 1.12.
Homologues: Orthologues: chimpanzee RAB39A (100% identical), macaque RAB39A (100% identical), rabbit RAB39A (99% identical), dog RAB39A (99% identical), pig RAB39A (99% identical), guinea pig RAB39A (98% identical), mouse Rab39 (97% identical), rat Rab39a (96% identical), zebrafish rab42a (55% identical). Paralogues in human: RAB39B (77% identical), RAB42 (46% identical), RAB2B (42% identical), RAB2A (40% identical), RAB11B (40% identical), RAB14 (40% identical), RAB33B (39% identical), RAB43 (39% identical), RAB11A (39% identical), RAB1A (38% identical), RAB4A (38% identical), RAB4B (38% identical), and 56 more.
Diseases named in the same sentence as RAB39A in open-access papers:
RAB39A is named in the same sentence as 17 diseases in open-access papers, as found by Europe PMC text mining. Sharing a sentence is not in itself a finding about the gene and the disease. The quoted sentences say what the papers report.
osteosarcoma (2 papers, 2018 to 2021). A usually aggressive malignant bone-forming mesenchymal neoplasm, predominantly affecting adolescents and young adults. "In 143B human osteosarcoma cells, the overexpression of RAB39A increased the SP fraction whereas the knockdown of RAB39A significantly decreased the SP fraction." (PMID 29515775, 2018). "The results obtained with osteosarcoma cells were confirmed for HeLa cells in which we found a higher expression of the CXCR4 stem cell marker, a higher SP fraction in cells overexpressing RAB39A, and a reduced CXCR4 expression and SP fraction in cells with knockdown of RAB39A." (PMID 29515775, 2018).
sarcoma (2 papers, 2018 to 2021). A usually aggressive malignant neoplasm of the soft tissue or bone. "We found that under hypoxia, RAB39A expression significantly increased in various cancer cell types, including sarcoma cells." (PMID 29515775, 2018). "Quantitative RT-PCR analysis of ∼400 human cancer tissues showed that RAB39A was highly expressed in sarcomas and in malignancies of lymphoid, adrenal and testicular tissues." (PMID 29515775, 2018). "Similarly, RAB39A was highly expressed in sarcomas and in malignancies of lymphoid, adrenal, and testicular tissues." (PMID 34550275, 2021). "Here, we found that RAB39A was expressed in malignancies originating from adrenal, lymphoid, pancreas and testicular tissues, with a higher level of expression (often 100-fold higher) in clinical sarcoma samples than other types of cancers." (PMID 29515775, 2018).
amyotrophic lateral sclerosis (1 paper, 2023). Amyotrophic lateral sclerosis (ALS) is a neurodegenerative disease characterized by progressive muscular paralysis reflecting degeneration of motor neurons in the primary motor cortex, corticospinal tracts, brainstem and spinal cord. "Activation of Rab39A is catalyzed by C9orf72, a guanine exchange factor associated with amyotrophic lateral sclerosis and familial frontotemporal dementia." (PMID 37821429, 2023).
chlamydial infection (1 paper, 2019). "Our results show that chlamydial infection did not alter the distribution of Rab39a at the late endocytic pathway and Rab39b at the early secretory route." (PMID 30987349, 2019).
sepsis syndrome (1 paper, 2013). "Our results also imply the possibility that Rab39a is a potent target molecule to control the sepsis syndrome because Rab39a regulates the inflammatory responses by controlling Caspase-1 activity and autophagy induction in response to LPS stimulation." (PMID 24349490, 2013).
thyroid carcinoma (1 paper, 2018). "To date, a high level of cytoplasmic expression of RXRB has been demonstrated in thyroid carcinoma; however, the expression of RAB39A has not been explored." (PMID 29515775, 2018).
triple-negative breast carcinoma (1 paper, 2018). An invasive breast carcinoma which is negative for expression of estrogen receptor (ER), progesterone receptor (PR), and human epidermal growth factor receptor 2 (HER2). "RXRB is also expressed in various malignancies and promotes cell survival/proliferation in triple-negative breast cancer, thus indirectly confirming a crucial role of the RAB39A-RXRB axis in modulating cancer stemness." (PMID 29515775, 2018).
cancer (5 papers, 2018 to 2021). A tumor composed of atypical neoplastic, often pleomorphic cells that invade other tissues. "The small GTPases Rab39A and B are potential new effectors of this pathway, as their malfunction is implicated in severe human diseases like cancer and neurodegeneration." (PMID 34638976, 2021). "RAB39A may thus be crucial for tumorigenesis since these processes are also linked to autophagy, which has an established role in cancer." (PMID 29515775, 2018). "RAB39A depletion was shown to decrease the colonization rate of certain cancer stem cells, while augmenting lipopolysaccharide-induced autophagosome formation in macrophages." (PMID 34638976, 2021). "Our data clearly demonstrated that RAB39A and its downstream molecular effector RXRB fostered cancer stemness and tumorigenesis, and that RAB39A-RXRB axis is a potential target for cancer therapies." (PMID 29515775, 2018). "This is the first time that RAB39A has been studied in cancer biology, with the exception of a report on mouse Neuro2A cells and their involvement in neuronal differentiation, such as retinoic acid-induced neurite morphology." (PMID 29515775, 2018). "In order to further explore the RAB39A downstream pathways that affect cancer stemness, we used RNA-seq to screen spheres produced by cells with a knockdown of RAB39A expression." (PMID 29515775, 2018). "Hypoxia is a trigger of cancer glycolysis; lysosomal compartmentalization is the most effective detoxification mechanism for high proton intracellular contents associated with glycolysis, and RAB39A activity might therefore be required for lysosomal acidification." (PMID 29515775, 2018). "Our data showed that RAB39A expression increased in hypoxic cancer cells and that its inhibition significantly reduced the viability of hypoxic CSCs." (PMID 29515775, 2018). "The RAB39A‒RXRB axis drives cancer stemness and tumorigenesis; consequently, the downregulation of this pathway leads to poor sphere formation and xenotransplantable function in several types of malignancies, such as sarcomas, adrenal, lymphoid, and testicular tumors." (PMID 33525614, 2021). "As RAB39A is involved in lysosome maturation and, according to our presented data, also in cancer stemness, we investigated whether hypoxia might modulate the expressions of RAB39A and RXRB, and mediate CSC survival under hypoxic conditions." (PMID 29515775, 2018). "Ras-like small GTPase activity contained in RAB39A may contribute to cancer developments through RXR and VDR signaling." (PMID 29515775, 2018). "In agreement with our speculation, our data clearly demonstrated that targeting RAB39A inhibits cancer stemness and tumorigenesis." (PMID 29515775, 2018). "Thus, targeting RAB39A-RXRB axis is a promising therapeutic approach to specifically affect the CSC fraction of the total cancer cell population that is also the tumor cell fraction associated with chemoresistance, recurrence, and metastasis." (PMID 29515775, 2018). "Among the candidate genes, RAB39A appears to be very promising since its knockdown had a clear impact on tumorigenicity in vivo, especially during the early steps of tumor formation, when cancer stemness has a major role." (PMID 29515775, 2018). "It is why inhibiting RAB39A or RXRB can critically affect cancer stemness." (PMID 29515775, 2018). "RAB39A and its downstream effector RXRB are associated with cancer stemness and tumorigenesis." (PMID 30338239, 2018). "Our previous report showed a clear connection between lysosomal acidification and cancer stemness, and we thus speculated that CSCs are particularly good targets for anti-RAB39A therapeutic strategies." (PMID 29515775, 2018). "Furthermore, our group recently found that retinol dehydrogenase 10 (RHD10), enzymes related to vitamin A metabolism and gluconeogenesis, can reflect cancer stemness through precise analyses of the RAB39A (a member of the RAS oncogene family)‒RXRB (retinoid X receptor beta) axis." (PMID 33525614, 2021).
cancer (continued). "Therefore, we suggest that RAB39A is involved in cancer stemness regulation." (PMID 29515775, 2018). "Together, the clinical sample data strengthen our hypothesis that RXRB is a downstream effector of RAB39A, and that RAB39A-targeting treatments will selectively affect cancer cells and be unlikely to cause undue side effects in normal tissues." (PMID 29515775, 2018). "Rab39a and its downstream effector Retinoid X Receptor Beta (RXRB), a member of the retinoid X receptor, are instead involved in cancer stemness regulation as silencing of Rab39a and inhibition of RXRB impairs tumorigenesis and cancer stemness." (PMID 31426400, 2019). "To confirm that RXRB is a downstream effector of RAB39A that fosters cancer stemness, we induced overexpression of RXRB in RAB39A-knockdown 143B cells and evaluated their sphere-formation ability and tumorigenesis in vivo." (PMID 29515775, 2018). "To further validate RAB39A and RXRB as potential targets for cancer therapy, we analyzed their expression levels in various malignancies from clinical samples." (PMID 29515775, 2018). "RAB39A and RXRB thus deserve further investigation that will allow the development of novel drugs for more effective and novel anti-cancer therapeutic strategies." (PMID 29515775, 2018). "In combination with a cellular functional analysis following RAB39A knockdown and RXRB augmentation, this strategy enabled us to identify RXRB as a downstream effector of RAB39A that fosters cancer stemness." (PMID 29515775, 2018). "Tokuhiro Chano then showed that RAB39A, a member of the RAS oncogene family, was selectively expressed in cancer cells and induced by hypoxia." (PMID 30338239, 2018). "On the other hand, some subpopulations of cancer cells could produce vividly growing spheres regardless of RAB39A repression." (PMID 33525614, 2021). "Among the top 100 gene elements on this axis, we selected 10 candidates, including RAB39A, CPVL, NUP210 and LHX2, which were robustly expressed in cancer cells and CSCs but not in normal MSCs or Fb in both acidic and neutral environments." (PMID 29515775, 2018). "Even though RAB39A-RXRB axis has never been described as a therapeutic option for cancers, here, it is proved that targeting RAB39A-RXRB axis significantly impairs cancer stem cell (CSC) growth and survival." (PMID 29515775, 2018).
infection (3 papers, 2013 to 2024). The state of being infected such as from the introduction of a foreign agent such as serum, vaccine, antigenic substance or organism. "We found that endocytic Rabs are selectively recruited to the vacuole of T. cruzi, among them Rab22a, Rab5, and Rab21 right away after the infection followed by Rab7 and Rab39a at later times." (PMID 33194787, 2020). "Because we found that the infection of E. coli induces the formation of LC3 punctuation in Rab39a-KD macrophages by immunofluorescence microscopy (data not shown), we examined the effect of Rab39a depletion on autophagy induction." (PMID 24349490, 2013).
tumor (2 papers, 2013 to 2018). "In the V5 controls from 143B cells, RAB39A-knockdown (V5_shRAB) caused significant reduction in tumor volume and rates of tumorigenesis compared to control cells (V5_shCont)." (PMID 29515775, 2018). "RAB39A knockdown in 143B tumor cell population also impaired the expression of the stem cell marker CD44 compared to control (shCont) cells." (PMID 29515775, 2018). "We also found six tumor related genes, TUSC2, TP53I3, TSSC4, RAB23, RAB39A, and ERG, which function as either tumor suppressor genes or oncogenes." (PMID 24007313, 2013).
RAB39A also shares sentences with these, for which no sentence is quoted: glioblastoma (1 paper); glioma (1); invasive breast carcinoma (1); leukemia (1); lymphoma (1); pheochromocytoma (1); testicular germ cell tumor (1).